EIF1AD (eukaryotic translation initiation factor 1A domain containing)
Description:
Plays a role into cellular response to oxidative stress. Decreases cell proliferation.
Synonyms: MGC11102; haponin; OBELIX
Tractability: Small molecule: a structure with a bound ligand is known. PROTAC: ubiquitination databases record sites on it; its protein half-life has been measured.
Gene: Protein-coding gene on chromosome 11 (65,996,545 to 66,002,472, reverse strand). Ensembl gene ENSG00000175376.
Subcellular location: Nucleus
Subcellular location (Human Protein Atlas): Nucleoplasm; Vesicles; Cytosol
Gene Ontology:
Molecular function: protein binding; RNA binding; translation initiation factor activity
Biological process: translational initiation
Cellular component: nucleoplasm; nucleus
Genetic constraint (gnomAD): Loss-of-function variants: 9 observed, 22.79 expected, observed/expected ratio (o/e) 0.39, 90% interval 0.24 to 0.69. The upper end of that interval is the gene's LOEUF score, 0.69, which puts it in group 2 of 6, group 1 being the genes least tolerant of losing a copy. Missense variants: 164 observed, 209.86 expected, observed/expected ratio (o/e) 0.78, 90% interval 0.69 to 0.89. Synonymous variants: 78 observed, 74.86 expected, observed/expected ratio (o/e) 1.04, 90% interval 0.87 to 1.26.
Homologues: Orthologues: chimpanzee EIF1AD (100% identical), macaque EIF1AD (99% identical), dog EIF1AD (98% identical), guinea pig EIF1AD (96% identical), rat Eif1ad (91% identical), mouse Eif1ad (90% identical), pig EIF1AD (82% identical), tropical clawed frog eif1ad (63% identical), rabbit EIF1AD (60% identical), zebrafish eif1ad (56% identical), Drosophila melanogaster CG31957 (41% identical), Caenorhabditis elegans ZK856.11 (34% identical).
Diseases named in the same sentence as EIF1AD in open-access papers:
EIF1AD is named in the same sentence as 14 diseases in open-access papers, as found by Europe PMC text mining. Sharing a sentence is not in itself a finding about the gene and the disease. The quoted sentences say what the papers report.
glioma (2 papers, 2019 to 2023). A benign or malignant brain and spinal cord tumor that arises from glial cells (astrocytes, oligodendrocytes, ependymal cells). "The fact that eIF1AD but not eIF1 or eIF1A, is abnormally expressed in gliomas should encourage studies aiming at elucidating its function, in particular in gliomas." (PMID 31795417, 2019). "KALRN, EIF1AD, DLL1, SH3RF1, and TLN1 are involved in neuronal structural integrity, plasticity, differentiation, and may contribute to the highly invasive nature of GBM as compared to other gliomas." (PMID 36834486, 2023).
gastric cancer (1 paper, 2025). A primary or metastatic malignant neoplasm involving the stomach. "This research explores the prognostic signature of MAGED2, KEAP1, GLA, EIF1AD, and EHF genes associated with hypoxia in gastric cancer through analyzing transcriptome information and scRNA-seq data, and indicates the clinical relevance of hypoxia during gastric cancer progression." (PMID 40129974, 2025).
tauopathy (1 paper, 2023). Neurodegenerative disorders involving deposition of abnormal tau protein isoforms (tau proteins) in neurons and glial cells in the brain. "We speculate that because of the role of EIF1AD in the formation of the ribosome, its down-regulation could cause ribosomal dysfunction and propitiate anomalous protein aggregation, given that translational impairment has been associated with tauopathies." (PMID 36316035, 2023). "Intriguingly, at least three gene products, VPS18, NUSAP1, and EIF1AD, were found to be down-regulated in the AD brain, supporting their potential relevance in the emergence or propagation of tauopathy." (PMID 36316035, 2023). "Furthermore, we showed that VPS18, NUSAP1, and EIF1AD are all down-regulated in AD brain samples, supporting the notion that these regulators may be important for the development of tauopathy in the human brain." (PMID 36316035, 2023).
EIF1AD also shares sentences with these, for which no sentence is quoted: tumor (2 papers); anorexia nervosa (1); autism spectrum disorder (1); bipolar disorder (1); brain diseases (1); breast tumor (1); bulimia nervosa (1); cancer (1); dementia (1); pharyngeal cancer (1); type 2 diabetes (1).